ACVR1 (activin A receptor type 1)
Diseases named in the same sentence as ACVR1 in open-access papers (continued):
Sharing a sentence is not in itself a finding about the gene and the disease.
gastric cancer (3 papers, 2021 to 2025). A primary or metastatic malignant neoplasm involving the stomach. "This pivotal observation marks the initial identification of the association between ACVR1 and gastric cancer onset triggered by H. pylori infection." (PMID 39924917, 2025). "In our previous study, we discovered that ACVR1 not only correlates with gastric cancer but also fosters the advancement of gastric cancer induced by H. pylori." (PMID 39924917, 2025). "Our previous study highlighted a potential involvement of ACVR1 in gastric cancer development triggered by H. pylori." (PMID 39924917, 2025). "Utilizing ACVR1 inhibitors may represent a new promising therapeutic strategy to alleviate gastric cancer lesions induced by H. pylori infection." (PMID 39924917, 2025). "Deregulated ACVR1 was reported to be related to gastric cancer progression." (PMID 34725559, 2021).
hepatocellular carcinoma (3 papers, 2019 to 2024). A malignant tumor that arises from hepatocytes. "ACVR1 was further highlighted as a regulator of stem cell markers, with the hepatocellular carcinoma CSC subtype featured by the miR-148a-ACVR1-bone morphogenetic protein (BMP)-Wnt circuit, whereby the expression of ACVR1 was suppressed by miR-148a." (PMID 30819221, 2019).
high-grade glioma (3 papers, 1996 to 2017). "Recent genomic studies of pediatric high-grade gliomas and DIPGs have revealed mutations in histone variant genes encoding histone proteins, Activin A receptor, type I (ACVR1) and protein phosphatase 1D (PPM1D) bringing new insights into the pathogenesis of these malignancies." (PMID 25200322, 2014).
lymphoma (3 papers, 2012 to 2024). A malignant (clonal) proliferation of B- lymphocytes or T- lymphocytes which involves the lymph nodes, bone marrow and/or extranodal sites. "ACVR1‐deficiency significantly reduces the sensitivity of lymphoma to PRC2 inhibitors both in vitro and in vivo." (PMID 38229201, 2024). "Furthermore, high levels of BMP6 and BMP7, along with ACVR1, are associated with longer survival in lymphoma patients, underscoring the clinical relevance of this study." (PMID 38229201, 2024). "In summary, immune synapse‐related genes are upregulated by PRC2 inhibition in responsive lymphomas and ACVR1 signaling strengthened this upregulation." (PMID 38229201, 2024). "We observed that ACVR1 mRNA levels are low in lymphoma, particularly in B‐cell lymphoma and DLBCL, among all the cancer cells in Cancer Cell Line Encyclopedia (CCLE)." (PMID 38229201, 2024). "Third, ACVR1 inhibition or deletion abolished the anti‐lymphoma effect of PRC2 inhibitors in cell culture and xenograft tumors, likely through blocking differentiation and immunological synapse‐mediated signaling in lymphoma." (PMID 38229201, 2024). "Elevated BMP6/7 and ACVR1 correlate with extended survival in lymphoma patients, underscoring its clinical relevance and potential usage as biomarker." (PMID 38229201, 2024). "Thus, we used two different ACVR1 inhibitors to reassure blocking ACVR1 signaling partially neutralized the anti‐lymphoma effect of MAK683." (PMID 38229201, 2024). "The genes BMP6, BMP7 and ACVR1 are directly repressed by PRC2 in lymphoma cells." (PMID 38229201, 2024). "Thus, ACVR1 deletion enables resistance to PRC2 inhibitors in lymphoma." (PMID 38229201, 2024). "In this study, Activin A Receptor Type 1 (ACVR1), a type I Bone Morphogenetic Protein (BMP) receptor, is identified as critical for the anti‐lymphoma efficacy of PRC2 inhibitors through a whole‐genome CRISPR screen." (PMID 38229201, 2024). "We checked the expression of known BMP ligands for ACVR1 and found that only BMP6 and BMP7 are expressed at high levels in lymphoma samples in CCLE and TCGA." (PMID 38229201, 2024). "As efficient tumor regression by PRC2 inhibitors requires ACVR1, does BMP‐ACVR1 signaling play a role in GC B cell maturation or lymphoma repression?" (PMID 38229201, 2024). "Through the differentially expressed genes (DEG) and GO analysis using RNA‐seq data from WSU‐DLCL2 lymphoma cell carrying EZH2Y641F, we observed an enrichment of TGF‐beta pathway with PRC2 inhibitor treatment, with BMP7 and ACVR1 as the top DEGs and multiple BMP ligands upregulated." (PMID 38229201, 2024). "As ACVR1 expression is low in lymphoma and PRC2 blocks its signaling, could artificially activating BMP‐ACVR1 signaling block lymphoma?" (PMID 38229201, 2024). "Together, the removal of H3K27me3 marks through PRC2 inhibition or depletion results in the upregulation of ACVR1 and the activation of BMP‐ACVR1 signaling, reflected by the phosphorylation of SMAD1/5 and the common upregulation of ID2 or ID3 in EZH2‐mutant lymphoma cells." (PMID 38229201, 2024). "Our study establishes a strong mechanistic and functional link between ACVR1 signaling and PRC2, suggesting that the BMP‐ACVR1 pathway may serve as an efficacy biomarker for PRC2 inhibitory drugs in lymphoma patients." (PMID 38229201, 2024).
osteoarthritis (3 papers, 2019 to 2024). A noninflammatory degenerative joint disease occurring chiefly in older persons, characterized by degeneration of the articular cartilage, hypertrophy of bone at the margins and changes in the synovial membrane. "Progeroid features in FOP that may primarily be associated with mutations in ACVR1 include alopecia, subcutaneous lipodystrophy, hearing loss, myelination defects, osteoarthritis, heightened inflammation, menstrual abnormalities, and perhaps nephrolithiasis." (PMID 31998237, 2019). "Progeroid features that may primarily be associated with mutations in ACVR1 include osteoarthritis, hearing loss, alopecia, subcutaneous lipodystrophy, myelination defects, heightened inflammation, menstrual abnormalities, and perhaps nephrolithiasis." (PMID 31998237, 2019). "ACVR1 was also up-regulated in hypertrophic chondrocytes taken from the articular cartilage of osteoarthritis patients." (PMID 39199396, 2024). "The inhibition of Acvr1-BMP signaling has successfully reduced osteoarthritis progression in mice." (PMID 39199396, 2024).
pulmonary hypertension (3 papers, 2021 to 2025). Increased pressure within the pulmonary circulation due to lung or heart disorder. "While hypercarbia from hypoventilation may be the main mechanism causing pulmonary hypertension, it is also hypothesized that dysregulated BMP signaling due to the Acvr1/Alk2 mutation may directly contribute to the development of pulmonary hypertension." (PMID 33562570, 2021).
breast tumor (2 papers, 2013 to 2023). "ACVR1C, TGFBR2, TGFBR3, ACVR2A, ACVR1, BMPR1A and BMPR2 were lower in breast tumours while ACVR1B and BMPR1B exhibited relatively higher expression levels in paired tumours compared with normal breast tissues, in the TCGA_BRCA cohort." (PMID 37333824, 2023).
cleft palate (2 papers, 2016 to 2019). Cleft palate is a fissure type embryopathy that affects the soft and hard palate to varying degrees. "Submucous cleft palate results from the overexpression of the Bmp receptor activin A receptor-type I (Acvr1), so appropriate levels and localization of Bmp pathway activity appear critical for correct tissue responses to palatogenic signaling." (PMID 30760477, 2019).
Infertility (2 papers, 2013 to 2024). "In a study conducted on mice lacking the ACVR1 gene, there was a delay in embryo invasion and implantation, and uterine stromal cells failed to undergo decidualization, resulting in infertility." (PMID 38492250, 2024).
lung carcinoma (2 papers, 2013 to 2023). "Activin plays a direct role in T-cell stimulation in the context of lung cancer through ACVR1." (PMID 37296966, 2023).
osteoporosis (2 papers, 2022). A condition of reduced bone mass, with decreased cortical thickness and a decrease in the number and size of the trabeculae of cancellous bone (but normal chemical composition), resulting in increased fracture incidence. "Since osteoporosis is a clinical feature in many advanced FOP patients, bone mass and architecture in the lumbar vertebrae (L4) of AAV-treated Acvr1(R206H)Fl;PDGFRα-cre mice were assessed by microCT and histology." (PMID 36258013, 2022).
pseudoexfoliation glaucoma (2 papers, 2020 to 2026). "Third, ACVR1 rs12997 associates across POAG, PACG, and pseudoexfoliation glaucoma (PXG), positioning BMP/TGF-β signaling as a shared mechanistic pathway spanning multiple subtypes." (PMID 42074148, 2026).
Truncus arteriosus (2 papers, 2015 to 2023). A single arterial trunk arises from the cardiac mass. "For example, neural crest-specific gene targeting of ACVR1/ALK2 impaired migration of these cells, disturbed the separation of the outflow tract, and caused persistent truncus arteriosus (PTA)." (PMID 25860837, 2015).
achondroplasia (1 paper, 2020). Achondroplasia is the most common form of chondrodysplasia, characterized by rhizomelia, exaggerated lumbar lordosis, brachydactyly, and macrocephaly with frontal bossing and midface hypoplasia. "For example, mutations in ACVR1, FGFR3, PTHrP, and GLI2 genes result in fibrodysplasia ossificans progressive (FOP), achondroplasia (ACH), brachydactyly type E2, and Culler–Jones syndrome, respectively." (PMID 32079226, 2020).
ankylosis (1 paper, 2024). Fixation and immobility of a joint. "Patients may present clinically with joint malformation and ankylosis, particularly in the cervical spine and costovertebral joints, as well as characteristic facial features and a litany of less common, non-skeletal symptoms, all stemming from missense mutations in the ACVR1 gene." (PMID 39199396, 2024).
B‐Cell Lymphoma (1 paper, 2024). "Second, PRC2 represses the expression of BMP6, BMP7, and ACVR1 by H3K27me3 in B cell lymphoma in vitro and in vivo." (PMID 38229201, 2024). "Finally, the high levels of BMP6, BMP7, and ACVR1 correlate with a favorable survival outcome in B‐cell lymphoma patients." (PMID 38229201, 2024). "Here, we investigated the mechanism of PRC2 inhibitors in B‐cell lymphoma using a whole‐genome CRISPR/Cas9 knockout (KO) screen and identified the Bone Morphogenetic Protein (BMP)‐Activin A Receptor Type 1 (ACVR1) signaling pathway is critical for the anti‐tumor efficacy of PRC2 inhibitors." (PMID 38229201, 2024).
calcific aortic valve disease (1 paper, 2022). "In addition, mice deficient in the Acvr1 gene have been shown to display a bicuspid aortic valve phenotype, which is a significant risk factor for the development of calcific aortic valve disease in humans." (PMID 36005436, 2022).
cardiac hypertrophy (1 paper, 2021). "As an essential member of TGF-β family, ACVR1 has the functional roles in early embryonic development, lens formation, chondrogenesis, osteogenesis and cardiac hypertrophy." (PMID 33431058, 2021).
Cardiomyopathies (1 paper, 2025). "These disorders are categorized into major clinical groups, such as Skeletal Dysplasias (e.g., analysis of genes like ACAN, ACP5, and ACVR1), Osteogenesis Imperfecta (COL1A1, COL1A2, BMP1), Metabolic Disorders (ACE, AGT, BICC1), and Cardiomyopathies, among others." (PMID 40282387, 2025).
colon cancers (1 paper, 2009). "Fifty-one population-based MSS colon cancers were assessed for ACVR1, ACVR2 and pSMAD2 protein." (PMID 20011542, 2009). "We show that in MSS colon cancers at least three members of the activin signaling cascade, ACVR2, ACVR1, and pSMAD2 are disrupted." (PMID 20011542, 2009). "To assess whether loss of receptor expression was due to loss of heterozygosity (LOH), a common genomic mechanism of tumor suppressor inactivation in MSS colon cancers, we assayed for LOH at the ACVR2 and ACVR1 gene loci." (PMID 20011542, 2009). "Of 51 MSS colon tumors, 7(14%) lost ACVR2, 2 (4%) ACVR1, and 5(10%) pSMAD2 expression." (PMID 20011542, 2009).
ependymoma (1 paper, 2023). A WHO grade II, slow growing tumor of children and young adults, usually located intraventricularly. "First, we observed increased expression of ACVR1 in PFAs compared to group B posterior fossa ependymomas (PFBs), a subtype of PF ependymomas that lacks EZHIP expression." (PMID 36759899, 2023).
gastritis (1 paper, 2025). Inflammation of the stomach. "Immunohistochemistry analysis showed elevated levels of ACVR1 in H. pylori-positive gastritis tissues, showing a negative correlation with POLD1 expression." (PMID 39924917, 2025). "The qRT-PCR analysis showed that the mRNA levels of ACVR1 was higher in H. pylori positive gastritis tissues, compared with H. pylori negative tissues, while POLD1 exhibited the opposite pattern." (PMID 39924917, 2025). "Similarly, we observed strong immunostaining of ACVR1 and γ-H2AX in gastritis tissues with H. pylori infection." (PMID 39924917, 2025).
Hallux valgus (1 paper, 2024). Lateral deviation of the great toe (i.e., in the direction of the little toe). "Furthermore, individuals with early onset recurrent HO, bilateral congenital hallux valgus malformations, and other features suggestive of FOP can undergo confirmatory genetic testing in the form of single-gene testing targeting the gain of function mutations in ACVR1." (PMID 38540768, 2024).
intervertebral disc degeneration (1 paper, 2022). "This study aimed to investigate the role played by microRNA (miR)-137 in intervertebral disc degeneration via targeting activin A receptor type I (ACVR1) and the underlying mechanism." (PMID 35236255, 2022).
intrauterine growth restriction (1 paper, 2014). "Of the many BMP ligands and receptors, Bmp2, Bmpr2 and Acvr1 have been previously shown to play important roles in endometrial function, with both early implantation (Bmp2 and Acvr1) and mid-gestational (Bmpr2) defects, some reminiscent of human intrauterine growth restriction." (PMID 24945252, 2014).
ischemia (1 paper, 2023). A hypoperfusion of the BLOOD through an organ or tissue caused by a PATHOLOGIC CONSTRICTION or obstruction of its BLOOD VESSELS, or an absence of BLOOD CIRCULATION. "In summary, fibrinogen deposition plays a critical role in the inhibition of OPC differentiation and remyelination during the progression of ischemia by targeting ACVR1." (PMID 36756722, 2023). "To determine whether NSC‐derived exosomal miR‐128‐3p is necessary for the modulation of ACVR1 activation and OPC differentiation in an in vitro model of ischemia, we treated OPCs with OGD." (PMID 36756722, 2023).
oral cancer (1 paper, 2025). "Screening of the data revealed eight TRGs (TGFB3, LTBP2, BMP2, TGFB1, ACVR1, CDK9, SLC20A1, and SMURF2) with non-zero coefficients, indicating their association with the prognosis of oral cancer patients." (PMID 38698292, 2025).
periodontitis (1 paper, 2025). An acute or chronic inflammatory process that affects the tissues that surround and support the teeth. "EV-derived miR-128-3p from LPS-induced periodontitis may cause renal inflammation and be mediated by the Rps6kb1, Tgfbr1, and Acvr1 genes through the TGF-β signaling pathway." (PMID 41440335, 2025).
preeclampsia (1 paper, 2013). Preeclampsia is a hypertensive disorder of pregnancy that is characterized by new-onset hypertension with proteinuria presenting after 20 weeks of gestation, and depending on mild or severe forms may initially present with severe headache, visual disturbances, and hyperreflexia. "In this group we have, for example, the HTRA1 and ACVR1 that have been well documented in preeclampsia." (PMID 24219996, 2013).
primary angle-closure glaucoma (1 paper, 2020). An angle-closure glaucoma characterized by closure of the anterior chamber angle by an intrinsic defect such that aqueous outflow is blocked and the intraocular pressure becomes inappropriately elevated leading to optic nerve damage and visual field loss. "It is difficult to elucidate the precise mechanism(s) by which the variant rs12997 in ACVR1 may influence the risk of these glaucoma types." (PMID 32641001, 2020). "Besides, based on the reports of miRNA-based regulation of ACVR1, understanding the underlying mechanisms of the ACVR1 gene biology may offer potential therapeutic drug target in glaucoma." (PMID 32641001, 2020).
Sepsis (1 paper, 2007). Sepsis is defined as life-threatening organ dysfunction caused by a dysregulated host response to infection. "Except for ACVR1 (activin receptor 1B) that was induced at 2 hours, most of the genes involved in growth regulation and recovering processes were upregulated during the second stage of sepsis." (PMID 17324256, 2007).
thyroid cancer (1 paper, 2010). "A significant inverse correlation was observed in the thyroid cancer samples for the L/R pair INHBB/ACVR1 (P<0.05), but not in the normal samples." (PMID 20877637, 2010). "Furthermore, other L/R pairs identified in our analysis, namely INHBB/ACVR1 and TNC/ANXA2, have been shown to be involved in invasiveness of other solid tumors, and as they have not yet been studied in thyroid cancer, warrant further investigation in this context." (PMID 20877637, 2010).
VEXAS syndrome (1 paper, 2026). An adult-onset inflammatory disease that affects only males and is caused by somatic, not germline, mutations. "Pacritinib, an oral inhibitor of IRAK1, JAK2, and ACVR1, has emerged as a promising therapeutic option for VEXAS syndrome." (PMID 41753113, 2026).